PCDHGA8 (protocadherin gamma subfamily A, 8)
Description:
Potential calcium-dependent cell-adhesion protein. May be involved in the establishment and maintenance of specific neuronal connections in the brain.
Synonyms: PCDH-gamma-A8; KIAA0327
Tractability: Antibody: UniProt places it where antibodies can reach, with medium confidence; UniProt predicts a signal peptide or a membrane-spanning region; its Gene Ontology location is reachable by antibodies, with medium confidence.
Gene: Protein-coding gene on chromosome 5 (141,390,157 to 141,512,975, forward strand). Ensembl gene ENSG00000253767.
Subcellular location: Cell membrane
Subcellular location (Human Protein Atlas): Plasma membrane; Vesicles; Cytosol; Nucleoplasm
Gene Ontology:
Molecular function: cell adhesion molecule binding; calcium ion binding
Biological process: cell adhesion; homophilic cell-cell adhesion
Cellular component: plasma membrane; membrane
Genetic constraint (gnomAD): Loss-of-function variants: 44 observed, 62.68 expected, observed/expected ratio (o/e) 0.7, 90% interval 0.55 to 0.9. The upper end of that interval is the gene's LOEUF score, 0.9, which puts it in group 3 of 6, group 1 being the genes least tolerant of losing a copy. Missense variants: 1,241 observed, 1,252.7 expected, observed/expected ratio (o/e) 0.99, 90% interval 0.94 to 1.04. Synonymous variants: 525 observed, 548.78 expected, observed/expected ratio (o/e) 0.96, 90% interval 0.89 to 1.03.
Homologues: Orthologues: mouse Pcdhga8 (83% identical). Paralogues in human: PCDHGA9 (80% identical), PCDHGA10 (77% identical), PCDHGA7 (76% identical), PCDHGA3 (76% identical), PCDHGA4 (75% identical), PCDHGA5 (75% identical), PCDHGA6 (75% identical), PCDHGA12 (74% identical), PCDHGA1 (74% identical), PCDHGA11 (74% identical), PCDHGA2 (73% identical), PCDHGB2 (50% identical), and 49 more.
Diseases named in the same sentence as PCDHGA8 in open-access papers:
PCDHGA8 is named in the same sentence as 1 disease in open-access papers, as found by Europe PMC text mining. Sharing a sentence is not in itself a finding about the gene and the disease.
PCDHGA8 shares sentences with these, for which no sentence is quoted: Sotos syndrome (1 paper).